WNK4 (WNK lysine deficient protein kinase 4)
Diseases named in the same sentence as WNK4 in open-access papers (continued):
Sharing a sentence is not in itself a finding about the gene and the disease.
pseudohypoaldosteronism type 2 (24 papers, 2007 to 2025). A rare inherited form of hypertension characterized by hyperkalemia, hyperchloremic metabolic acidosis, normal or elevated aldosterone, low renin, and normal renal function. "Mutations in the genes encoding WNK1 and WNK4, among others, are cause of a tubulopathy called familial hyperkalemic hypertension (FHHt) (also known as pseudohypoaldosteronism type II or Gordon syndrome)." (PMID 40668923, 2025). "Mutations in WNK1 and WNK4 are associated with familial hyperkaliaemic hypertension (FHHt) or pseudohypoaldosteronism type II (PHAII) (OMIM: 145260) as a result of increased NCC activity." (PMID 32603001, 2021). "In mice and humans, mutations in WNK4 that cause kinase overexpression are the cause of Familial Hyperkalemic Hypertension (FHHt), a disease that is mainly the consequence of the upregulation of NCC activity." (PMID 33192599, 2020). "Gain-of-function mutations in genes encoding for WNK1 or WNK4 cause Familial Hyperkalemic Hypertension (FHHt), also known as pseudohypoaldosteronism type 2 or Gordon’s syndrome." (PMID 32659887, 2020). "Point mutations in WNK4 have been associated in humans with the dominant disorder familial hyperkalemic hypertension and characterized by dysfunction in renal Na+, K+, and Cl− homeostasis." (PMID 23285264, 2012). "WNK1 and WNK4 are known to be responsible genes of pseudohypoaldosteronism type 2 (PHA2) that is caused by large deletions in intron 1 of WNK1 or gain-of function mutations in WNK4." (PMID 36009402, 2022). "The first evidence linking WNK kinases to the CCCs was the discovery of mutations in the genes WNK1 and WNK4 in Familial Hyperkalemic Hypertension (FHHt), also known as Pseudohypoaldosteronism type 2 (PHAII), or Gordon syndrome." (PMID 33192599, 2020). "Pseudohypoaldosteronism type 2 (PHA2), also known as Gordon syndrome, is a rare genetic disorder associated with variants in WNK1, WNK4, KLHL3, and CUL3." (PMID 39527282, 2025). "Impaired WNK4 ubiquitination plays a key role in Familial hyperkalemic hypertension (FHHt, also called pseudohypoaldosteronism type II) which results from overaction of thiazide-sensitive sodium chloride cotransport (NCC)." (PMID 37481568, 2023). "Pseudohypoaldosteronism type II (PHAII), characterized by hypertension, hyperkalemia, and metabolic acidosis, results from mutations in WNK kinase family members WNK1 and WNK4." (PMID 32714200, 2020). "WNK4 is the major regulator of the Na-Cl co-transporter in the kidney, a regulator of adipogenesis and energy metabolism and a causal gene for pseudohypoaldosteronism type II, but has no known role in chondrocyte hypertrophy." (PMID 29659575, 2018). "Moreover, these authors found that transgenic mice overexpressing WNK4 exhibit pseudohypoaldosteronism type II (PHA-II), suggesting that WNK4 positively regulates NCC." (PMID 26491696, 2015).
Hyperkalemia (14 papers, 2009 to 2025). An abnormally increased potassium concentration in the blood. "Since this feature is not present in KS-WNK1–KO mice, our findings suggest that KS-WNK1 recruits an auxiliary mechanism that promotes NCC dephosphorylation during hyperkalemia, independently of WNK4-SPAK/OSR1 signaling." (PMID 40493421, 2025). "In contrast, in regard to their effect on ROMK, the same mutations may increase the activity of WNK4, further enhancing the suppressive effect of WNK4 on ROMK and explaining the hyperkalemia." (PMID 17647025, 2009). "Klhl3R528H/+ knock-in mice showed an increased abundance of WNK1, WNK4, and phosphorylated NCC in mouse kidney samples while exhibiting classical FHHt phenotypes of salt-sensitive hypertension, hyperkalemia, and metabolic acidosis." (PMID 37845702, 2023). "The WNK4 phosphorylation by cSrc or SGK1, activated by angiotensin II or aldosterone, respectively, is another relevant mechanism of NCC, ENaC, and ROMK modulation in states such as volume reduction, hyperkalemia, and hypokalemia." (PMID 36790288, 2023).
Gordon syndrome (13 papers, 2007 to 2023). An extremely rare multiple congenital malformation syndrome characterized by congenital contractures of hand and feet with variable degrees of severity of camptodactyly, clubfoot and, less frequently, cleft palate. "The KLHL3 interaction site in WNK1 is on a non-catalytic region, which is interestingly the equivalent site on WNK4, which encompasses mutated residues in Gordon syndrome patients." (PMID 31795491, 2019). "Mice transgenic for a WNK4 missense mutation (TgWnk4PHA2) seen in Gordon syndrome show activation of Pendrin activity (an anion exchange protein encoded by SLC26A4), suggesting WNK4 is involved in Pendrin activation." (PMID 31795491, 2019). "The phenotypic severity of Gordon syndrome varies according to different causative mutations (CUL3 > recessive KLHL3 > dominant KLHL3 > WNK4 > WNK1)." (PMID 31795491, 2019). "Replacement of KLHL3 Gordon's syndrome-causing mutations located within the Kelch domain (R528H or N529K) reduced binding to the WNK4 degron peptide approximately 10-fold." (PMID 24641320, 2014). "Consistent with the acidic region operating as a degron motif, recent work has revealed that a WNK4 knock-in mouse displaying a Gordon's syndrome mutation within this motif (WNK4 [D561A]) possesses markedly elevated levels of WNK4 in the kidney." (PMID 24641320, 2014). "The findings of the present study also emphasize that the missense mutations in WNK4 thatcause Gordon's syndrome strongly inhibit interaction with KLHL3." (PMID 23387299, 2013). "WNK4 mutations (PHA2B) were also subsequently identified in Gordon syndrome patients." (PMID 31795491, 2019). "Furthermore, it offers a structural explanation for the disruptive effects of a number of Gordon's syndrome mutations that are described in WNK4 and the Kelch domain of KLHL3." (PMID 24641320, 2014). "Mutations in WNK1 and WNK4 cause familial hypertension, the Gordon syndrome." (PMID 21520334, 2011). "The finding that disease-causing mutations ofGlu562 and Gln565 markedly impair binding to KLHL3 is very exciting, as thissuggests that loss of interaction with CUL3–KLHL3 may lie at the heart of understanding howmissense mutations in these residues of WNK4 results in Gordon's syndrome." (PMID 23387299, 2013). "In humans, WNK1, WNK4, CUL3, and/or KLHL3 mutations manifest as Gordon’s syndrome, a heritable form of hypertension associated with salt-sensitive hypertension, hyperkalemia, metabolic acidosis, and thiazide sensitivity." (PMID 36028759, 2022). "Pseudohypoaldosteronism type II (PHAII), also called Gordon syndrome, is a rare hereditary disease caused by variants in the WNK1, WNK4, KLHL3 and CUL3 genes." (PMID 34022862, 2021). "Since the recognition of this predominantly autosomal dominant condition in the 1960s, the study of families with Gordon syndrome has revealed four genes WNK1, WNK4, KLHL3, and CUL3 to be implicated in its pathogenesis after a phenotype–genotype correlation was realised." (PMID 31795491, 2019). "Mutations within a non-catalytic highly acidic motif of WNK4 located C-terminal to the kinase domain (residues 557–567) also cause Gordon's syndrome." (PMID 24641320, 2014). "Missensemutations in the related WNK4 gene that alter three close-by non-catalytic residues(Glu562, Asp564 and Gln565) also cause Gordon's syndrome." (PMID 23387299, 2013). "In contrast, other transgenic murine studies where WNK4 was significantly overexpressed (two-fold higher levels of WNK4 kidney protein) produced increased phosphorylation of OSR1, SPAK, and NCC in the kidney, leading to a Gordon syndrome phenotype." (PMID 31795491, 2019). "When expressed in Xenopus oocytes and in mice, ENaC activity is not inhibited by the Gordon syndrome mutant WNK4 and subsequent increased ENaC activity is seen in the kidney and colon in these mutant models." (PMID 31795491, 2019).
Hypokalemia (8 papers, 2012 to 2025). An abnormally decreased potassium concentration in the blood. "The WNK4 mutation in the Burmese cat is linked for the first time with hypokalemia in a mammalian species; a novel model for human disease." (PMID 23285264, 2012). "Thus, altered function in WNK4 causes loss of potassium in the urine in kittens, which in turn results in symptomatic hypokalemia." (PMID 35158718, 2022). "Moreover, the identified mutation may help clarify the role of the protein in K+ regulation and the cat represents the first animal model for WNK4-associated hypokalemia." (PMID 23285264, 2012). "The severe hypokalemia developed in the double knockouts under dietary K+ restriction was reminiscent to the one observed in WNK4–/– mice on this same condition." (PMID 33192599, 2020). "Labeling of SPAK, a kinase downstream of lysine-deficient protein kinase 1 (WNK1) and WNK4 and upstream of NCC, demonstrated increased intensity and abundance of punctuated condensates resembling hypokalemia-related WNK+ bodies in the index patient compared with control samples." (PMID 39405114, 2024). "The signaling pathways activated by AngII and Aldo can interfere directly with phosphorylation of WNK4 in different residues, but the electrolyte changes induced by Aldo, as hypokalemia, have also to be considered as important and independent modulators of WNK4 activity." (PMID 36790288, 2023). "Hypokalemia, on the other hand, increases NCC activity through WNK4-SPAK, at the same time that ENaC and ROMK are inhibited by WNK4." (PMID 36790288, 2023). "Kir4.1/Kir5.1 deletion results in depolarization of the basolateral membrane of DCT cells, decreases NCC activity by inhibiting the WNK4/SPAK pathway, increases the Na+ load to principal cells, and induces hypokalemia." (PMID 36790288, 2023). "Thus, although the WNK4 gene mutation identified in domestic cats was absent in the lions, other alterations in or near the gene may result in downregulation of the transcription of the gene or mRNA stability resulting in hypokalemia and polymyopathy." (PMID 35158718, 2022). "No upregulation of NCC phosphorylation is observed in WNK4–/– mice and, consequently, mice develop severe hypokalemia when maintained on a low K+ diet." (PMID 33192599, 2020). "Since angiotension II-dependent WNK4-SPAK-(p)NCC activation was present in CMA, the AT1R blocker and/or NCC inhibitors should be used with caution in such setting to avoid the exacerbated natriuresis, worsening metabolic acidosis and even hypokalemia." (PMID 26728390, 2016). "Through the analysis of WNK4D561A/+ PHAII model mice crossed with Osr1 and Spak knock-in mice, we showed that the pathogenesis of hypokalaemia is also the result of NCC activation by WNK–OSR1/SPAK signalling, but is not caused by a direct effect of mutant WNK4 on ROMK." (PMID 24655003, 2014). "Hypokalemia activates the renal sodium chloride cotransporter (NCC) along the distal convoluted tubule (DCT), at least in part, through with-no-lysine 4 (WNK4) kinase and STE20/SPS1-related proline-alanine-rich protein kinase (SPAK) signaling." (PMID 40759567, 2025).
Obesity (3 papers, 2021 to 2022). Accumulation of substantial excess body fat. "Obesity provides major attenuation of NFκB signaling via SOCS3-associated JAK2 inhibition, and then suppresses WNK4 activity." (PMID 34489970, 2021). "In brief, upregulation of the WNK4 cascade in obesity is consistent with the condition of chronic inflammation." (PMID 34489970, 2021). "Nevertheless, the interaction between SOCS3 and WNK4 in modulating VILI in obesity warrants further investigation." (PMID 34489970, 2021). "In nonobese mice, SOCS3 augmentation (CD + hesperetin) resulted in a trend toward WNK4 upregulation, albeit to a much lesser extent compared with the effect of obesity itself." (PMID 34489970, 2021). "It’s supposed the predicted aggravation of lung injury in WNK4 knockin wild-type mice is offset by the protection of obesity." (PMID 34489970, 2021). "This also suggests that SOCS3 only partly accounts for the upregulation of the WNK4–SPAK cascade in obesity." (PMID 34489970, 2021). "After VILI, the activation of WNK4 in mice was slightly modulated by obesity and the manipulation of SOCS3 expression." (PMID 34489970, 2021). "However, the interaction between SOCS3 and WNK4 axis in regulating VILI in the context of obesity warrants further investigation." (PMID 34489970, 2021). "To determine whether obesity also affected WNK4 axis and AFC, we briefly examined the role of obesity in the WNK4–SPAK pathway." (PMID 34489970, 2021). "Obesity protects lungs from VILI by upregulating SOCS3, thus suppressing the STAT3/NFκB inflammatory pathway and enhancing WNK4-related AFC." (PMID 34489970, 2021). "Most importantly, obesity itself had a protective function against VILI and predominated over the effect of WNK4 manipulation." (PMID 34489970, 2021). "In summary, obesity modulated both the STAT3/NFκB pathway and the WNK4 axis." (PMID 34489970, 2021). "The severity of VILI in WNK4-knockin obese mice was counteracted by obesity, similar to that of wild-type nonobese mice only." (PMID 34489970, 2021). "WNK4 (with-no-lysine kinase 4), a substrate of the CUL-KLHL3 E3 ligase complex, is an adipogenic factor whose deletion reduces high-fat (HF) diet-induced obesity in mice." (PMID 36028759, 2022).
breast carcinoma (2 papers, 2022 to 2023). "Besides this, ID4, SEMA3F, FOXD, KCNK5, WNK4 and ECM1 associate with chemoresistance origin and SOX5, ITM2A, SNCG, EPHA4, NTS, FGFR2 and ENPEP associate moreover with breast cancer tumorigenesis." (PMID 37239828, 2023).
diabetes (2 papers, 2016 to 2017). "Taken together, these findings demonstrate that diabetes increases WNK4 phosphorylation at serine residues mediated by SGK1 activity." (PMID 28493961, 2017). "It was found that diabetes induces mRNA and protein expression of WNK4, and SPL treatment significantly prevented these changes." (PMID 28493961, 2017). "Herein we found that diabetes increases the TJ localization, transcription and protein level of WNK4." (PMID 28493961, 2017). "It was found that diabetes increased co-IP of WNK4 with cldn-4; these findings were confirmed by reverse IP." (PMID 28493961, 2017). "It was found that diabetes increases the WNK4 label in both cytoplasm and intercellular junctions of DT, where a diffuse label is observed (green color)." (PMID 28493961, 2017). "Also, co-IP assays showed that diabetes induces the interaction of SGK1 with WNK4, which was prevented by SPL." (PMID 28493961, 2017). "Also, it was found that diabetes promotes WNK4 co-localization with cldn-4 and -8 in the TJ, thus suggesting that WNK4 interacts directly and phosphorylates cldn-4 and -8 on threonine residues." (PMID 28493961, 2017). "Herein it was found that diabetes induced serine phosphorylation of WNK4." (PMID 28493961, 2017). "The distribution of allele frequency and genotype of WNK4 gene Ala589Ser polymorphism showed significant differences (p < 0.05) between EHT subjects with or without type 2 diabetes mellitus (T2DM) and normotensive subjects, statistically." (PMID 27314050, 2016). "Diabetes increased SGK1 expression and induced its co-immunoprecipitation with WNK4." (PMID 28493961, 2017). "To further corroborate whether diabetes alters the phosphorylation of WNK4 by SGK1, we analyzed the SGK1 expression in the four experimental groups and found that diabetes induces SGK1 expression and SPL significantly prevented these changes." (PMID 28493961, 2017). "Furthermore, phosphorylation of WNK4 was analyzed and it was found that diabetes increases serine but not threonine phosphorylation of WNK4." (PMID 28493961, 2017).
Hypercalciuria (2 papers, 2007 to 2019). "Following acute treatment with the loop diuretic, furosemide, which causes hypercalciuria through TAL inhibition, WNK4−/− animals demonstrated increased calcium wasting compared with wild‐type controls." (PMID 31496133, 2019). "Pseudohypoaldosteronism (PHA) type II from with-no-lysine kinase 4 (WNK-4) mutation can cause hypercalciuria from its role in regulation of TRPV5, whereas dRTA leads to hypercalciuria indirectly from metabolic acidosis and increased bone resorption." (PMID 17464515, 2007). "However, we found increased hypercalciuria following acute furosemide administration in the absence of WNK4, which is the opposite of which this mechanism would indicate." (PMID 31496133, 2019).
asthma (1 paper, 2020). "The disease–gene association p-value scores (−1og10) in moderate asthma-related genes ranged from 3.2 (ZNF862) to 6 (PER2), while in severe asthma-related genes, it varied from 2.2 (TMCC1) to 6 (SLCO1B3, and WNK4)." (PMID 32512817, 2020). "In moderate-to-severe asthma-related genes, it ranged from 3 (AIM1L) to 7.73 (WNK4)." (PMID 32512817, 2020).
edema (1 paper, 2020). An abnormal accumulation of fluid beneath the skin, or in one or more cavities of the body. "Severe pulmonary edema, increased expression of pro-inflammatory cytokines, neutrophils, and AM1 infiltration, and the activation of the WNK4–SPAK–NKCC1 pathway were observed in rats with ALI." (PMID 32645929, 2020). "ALI presents with severe pulmonary edema, inflammation, increased infiltration of neutrophils and AM1, and activation of the WNK4–SPAK–NKCC1 pathway." (PMID 32645929, 2020).
Hyperchloremia (1 paper, 2024). An abnormally increased chloride concentration in the blood. "Functional enrichment analysis revealed that oral poisoning owing hyperchloremia is associated with 4 proteins e.g. Kelch-like protein 3, Serine/threonine-protein kinase WNK4, Serine/threonine-protein kinase WNK1 and Cullin-3." (PMID 38615119, 2024).
influenza infection (1 paper, 2019). "We further detected the protein expression of ENaC and found that the decreased ENaC protein levels via influenza infection were relieved by WNK4 knockdown." (PMID 30723408, 2019). "As a PKC downstream, we speculated that WNK4 would be activated to regulate ENaC activity via influenza infection." (PMID 30723408, 2019).
ischemia (1 paper, 2022). A hypoperfusion of the BLOOD through an organ or tissue caused by a PATHOLOGIC CONSTRICTION or obstruction of its BLOOD VESSELS, or an absence of BLOOD CIRCULATION. "For example, loss of WNK3 may reduce ischemia-associated brain damage, whereas mutations in WNK1 and WNK4 disrupt renal salt uptake to induce pseudohypoaldosteronism type II (PHAII)." (PMID 35179207, 2022).
ischemic stroke (1 paper, 2019). A stroke disorder caused by obstruction of blood flow to the brain, due to thrombotic (local blood clot formation) or embolic (due to a blood clot or other material traveling from another site) event. "In light of expression of WNK4 in the BBB endothelium and increased level in ischemic stroke of hypertensive rats, future studies are needed to elucidate roles of WNK4 in the CNS, especially considering to its high sensitivity to [Cl]i." (PMID 31165006, 2019).
neuroblastoma (1 paper, 2022). Neuroblastoma (NB) is the most common solid, extracranial childhood tumor. "We have previously reported that WNK1 and WNK4 are involved in induction of neural marker genes and neurite elongation in mouse neuroblastoma Neuro2A cells." (PMID 36151370, 2022).
osteoporosis (1 paper, 2025). A condition of reduced bone mass, with decreased cortical thickness and a decrease in the number and size of the trabeculae of cancellous bone (but normal chemical composition), resulting in increased fracture incidence. "Abnormal activation or inhibition of BRAF could directly interfere with osteogenesis, while WNK4, a kinase primarily regulating ion transport and cellular homeostasis, shows a strong binding affinity with TPhP, suggesting that TPhP may promote osteoporosis by disrupting ion balance." (PMID 40692598, 2025). "The LASSO regression algorithm established an osteoporosis-related model, identifying six disease-related candidate core target genes (IGF1R, NR3C1, MAP3K1, BRAF, WNK4, CNR2)." (PMID 40692598, 2025).